PCNA (proliferating cell nuclear antigen)
Diseases named in the same sentence as PCNA in open-access papers (continued):
Sharing a sentence is not in itself a finding about the gene and the disease.
tumor (continued). "PCNA is an essential protein involved in multiple processes of DNA metabolism, and targeting PCNA has been shown to be an effective strategy to inhibit tumor cell proliferation." (PMID 35220878, 2022). "Treatment with Thymax inhibited cellular proliferation by decreasing the expression of tumor markers Ki-67, PCNA, and Cyclin D1 in cancer cells and increasing the expression of p21 and p27." (PMID 35299600, 2022). "This inhibits the PCNA action on the replication forks and indirectly leads tumor cells to a higher sensitivity to anticancer DNA damaging drugs." (PMID 35677658, 2022). "The proliferation of tumor cells is correlated with a high degree of tumor malignancy, which can be evaluated by measuring the PCNA protein expression." (PMID 35216113, 2022). "H&E, PCNA, and Tunel stained tumor slices showed that tumor necrosis was increased, proliferation was decreased, and cell death was induced in the protoporphyrin group compared with the normal saline group." (PMID 34975339, 2022). "Studies have confirmed that several tumor aggressiveness markers like PCNA have high expression, providing molecular evidence for the relationship between apnea and cancer." (PMID 35132330, 2022). "Treatment of mice with both μ-21-ON and μ-21-ON/μ-17-ON/μ-155-ON led to an almost 2-fold decrease in the number of PCNA-positive tumor cells compared with the control groups, being equal to 35% of PCNA-positive cells." (PMID 36139555, 2022). "The effect of Thymax on Ki-67 and PCNA protein expression in tumor tissues of the Inocul Control mice was examined with flow cytometry measurements of protein expression in tumor tissues, immunohistochemical analysis, and measurements of labeling indices." (PMID 35299600, 2022). "The expression level of PCNA proteins in tumor cells reflects the degree of cell proliferation and can be used as an index to evaluate cell apoptosis." (PMID 35268705, 2022). "Ki67 and PCNA were shown to be strongly expressed in stained cells in previous investigations, implying that tumor cells were active and proliferated rapidly." (PMID 35978996, 2022). "The pro-invasive signature genes include 57 of 131 genes in the tumor proliferation signature meta-PCNA gene set34 (FET OR = 36.8 and p = 5.3 × 10−57)." (PMID 35332150, 2022). "Together, these results showed that the WT/PyMT cancer cells harbored a higher tumor initiation activity compared to the 211F/PyMT cells, supporting a function for Y211 phosphorylation in PCNA in cell stemness during tumorigenesis." (PMID 35628489, 2022). "Loss of phosphorylation at tyrosine 211 (Y211) in PCNA (pY211-PCNA) mitigates PCNA function in proliferation, triggers replication fork arrest/collapse, which in turn sets off an anti-tumor inflammatory response, and suppresses distant metastasis." (PMID 35628489, 2022). "In our previous study, we developed a cell-penetrating NKp44-derived linear peptide also capable of cell penetration, R11-NLS-pep8, which can specifically interact with nuclear PCNA and mediates tumor cell death." (PMID 36430528, 2022). "The expression level of cell cycle‐related proteins, such as cyclin D1, cyclin E, Cdk2, Cdk4, Cdk6, and PCNA was also decreased in anti‐Chi3L1 antibody‐treated lung metastasis tumor tissue." (PMID 34861103, 2022). "Accordingly, IHC experiments further revealed that Ki-67 and PCNA, indicators of proliferation, were notably up-regulated in tumors derived from shSPTBN1 786-O cells, indicating more rapid tumor growth." (PMID 36527113, 2022). "The cordycepin group in our study had higher tumor-related protein (cyclin D, PCNA, and Ki-67) expression levels than the control group." (PMID 36142286, 2022). "Immunohistochemical staining of RLS40 tumor sections with PCNA-specific primary antibodies demonstrated that 61.1 ± 1.9% and 76.3 ± 3.2% of tumor cells were PCNA-positive in the control and μ-Scr-ON groups, respectively." (PMID 36139555, 2022).
tumor (continued). "Grain-sized moxibustion down-regulated the expression of proliferation genes Ki67 and PCNA, weakened the proliferation ability of Hepa1-6 tumor cells, inhibited tumor growth, and enhanced the antitumor effect of CTX." (PMID 35978996, 2022). "Protein analysis also showed similar results that treatment with BDDD-721 and curcumin reduced the proliferation Ki67 and PCNA of xenograft tumor, and the inhibition effect of BDDD-721 was stronger at the same dose." (PMID 35802536, 2022). "Given the important role of PCNA in initiation of cell proliferation, PCNA is considered a good indicator of the state of tumor cell proliferation." (PMID 35911648, 2022). "In our study, RTP was found to significantly (p < 0.05) reduce PCNA expression in tumor tissue, potentially by inhibiting tumor size and weight." (PMID 35269987, 2022). "IHC staining showed that a stronger PCNA intensity was observed in tumours induced by higher CSTB‐expressing cells." (PMID 36495123, 2022). "Decreased expression of PCNA in the tumor tissue suggests the low proliferative activity of tumor cells." (PMID 34466749, 2022). "Expressions of both cyclin E1 and PCNA in DKO tumours were also increased to a similar level as that of WT tumours." (PMID 35867177, 2022). "It was shown that HMGB1 induces proliferation of tumor cell and expression of PCNA through ERK1/2 pathway to promote the occurrence of IBD-related CRC, while GSDME-mediated pyroptosis can release HMGB1." (PMID 36092900, 2022). "The immunohistochemical analysis in the tumor tissues for the expression status of cell proliferation markers, PCNA and Ki67, and the apoptosis marker, cleaved PARP, revealed the augmented potency of Utt-B over sorafenib." (PMID 35631464, 2022). "The synthesis and expression of PCNA promote in proliferating cells, which represents cell proliferation and is considered as a reliable index for evaluating tumor cell proliferation." (PMID 35782078, 2022). "Results of the present study showed that Thymax treatment significantly decreased tumor cell proliferation as indicated by marked suppression in the expression of PCNA, Ki-67, and Cyclin D1 in cancer cells." (PMID 35299600, 2022). "In contrast to the PBT24 tumor, the SF8628 tumor’s PCNA and EZH2 expressions were sensitive to 2.5 mM MgDCA." (PMID 36142368, 2022). "Ki67 and PCNA protein expression levels were selected as indices of tumor tissue proliferation for immunohistochemical detection and analysis." (PMID 36242003, 2022). "We also found that miR-300 expression was overexpressed in lung tumor tissues, and that miR-300 suppression inhibited tumor cell proliferation as evidenced by reduced Ki67 and PCNA expression, and lower invasion and migration." (PMID 35501353, 2022). "This impact was ascribed to an increase in proliferating cell nuclear antigen (PCNA) positive cells in tumor, which is a sign of enhanced cancer cell proliferation in vivo." (PMID 36059497, 2022). "In vivo, Nr‐CWS inhibited tumor growth and decreased the expression of E6, E7, PD‐L1, P16, Ki67, and PCNA in tumors." (PMID 34994088, 2022). "FAT10 binds with PCNA, leading to proteasomal degradation of PCNA in the nucleus and cytoplasm, leading to increased tumor cell invasion." (PMID 36386217, 2022). "PCNA, Bax, and Bcl-2 have been confirmed by a large number of studies to be important proliferation and apoptosis proteins that can reflect the anti-tumor effect of drugs in breast cancer." (PMID 35911648, 2022). "HE and PCNA analysis of tumor pathological tissue further revealed that overexpression of MINPP1 gene inhibits the proliferation of tumor cells." (PMID 33390177, 2021). "Taken together, LPEPS oral administration promotes the tumor apoptosis by down-regulating PCNA and up-regulating caspase cascade." (PMID 34945611, 2021).
tumor (continued). "The analyses of tumour cell proliferation were confirmed by Ki67 staining and immunoblotting of PCNA." (PMID 34380537, 2021). "The results indicated that combining sorafenib with either compound significantly suppressed tumor proliferation and increased apoptosis evidenced by PCNA and cleaved-caspase (c-caspase 3) staining." (PMID 35174171, 2021). "We further examined the proliferation activity of tumours by examining the expression status of PCNA using IHC." (PMID 33713546, 2021). "Immunohistochemical analyses of the human GBC cells xenografted in nude mice showed a low Ki67 and PCNA expression in KIF11-knockdown tumor tissues which were identified with the previous results." (PMID 33613109, 2021). "CAF-1 (in particular CHAF1B) expression in a wide range of tumours displays a strong correlation with the prototype cell proliferation marker Ki-67 and other proliferation markers (PCNA, MCMs, and ASF1b)." (PMID 34073937, 2021). "It is well documented that decreased PCNA and CCND1 expression is associated with retarded proliferation of tumor cells and that reduced MMP9 and Vimentin expression is closely related to slowed invasion of cancer cells." (PMID 34511432, 2021). "All the previous findings indicate the essential role of PCNA in the tumor regulation of BC, which perhaps explains why overexpression of PCNA had a significant recovery effect on tumor growth inhibition induced by FBXO43 interference." (PMID 34645483, 2021). "There was a decrease of PCNA expression in Lenti‐shHAX1 groups which indicated HAX1 knockdown inhibited the tumour growth." (PMID 34755451, 2021). "Ki67 and proliferating cell nuclear antigen (PCNA) are the common proliferative markers in tumor growth." (PMID 34666596, 2021). "Further analysis revealed that while PCNA was overexpressed in CC tissues, it was correlated with favorable prognosis (log-rank P=0.022, HR=0.58) and tumor purity (P=9.86 × 10-4, partial rho=0.197) in CC patients." (PMID 34900731, 2021). "Analysis of cyclin A, cyclin B and PCNA (an additional classical marker of proliferation) expressions in the tumor punches (TM) from PK+/+ and PK-/- mice shows an accumulation of these proteins in PK-/- TM punches when compared to PK+/+." (PMID 34815803, 2021). "Overexpression of peroxiredoxin 1 significantly promotes proliferation and inhibits apoptosis by increasing the expression of PCNA in human CC tissue and is closely related to tumor staging, lymphatic metastasis, and differentiation." (PMID 34721621, 2021). "IHC results showed that CD36-positive tumor cells are accompanied by higher PCNA-nuclear expression." (PMID 33771982, 2021). "NK cell activity can also be suppressed by the interaction of NKp44 receptor with proliferating cell nuclear antigen (PCNA), which is overexpressed on the surface of many types of tumor cells." (PMID 34768814, 2021). "We found that the expressions of tumor proliferation-related markers PCNA and C-myc were reduced in SMMC-7721 cells transfected with sg-MCCC2-1 and sg-MCCC2-3 and found that the expression of N-cadherin, a mesenchymal cell-specific marker, decreased." (PMID 33407468, 2021). "Consistently, IHC results showed the marked reduction of the proliferating cell nuclear antigen (PCNA) marker of proliferating cells in the tumor tissues of 2′-HCA-treated mice." (PMID 34834209, 2021). "The PCNA exists in normal proliferative cells and tumor cells, PCNA was also a major endogenous marker for testing the cell proliferation ability." (PMID 34679029, 2021). "On day 27 of cell injection, the volume and weight of the tumor, as well as PCNA, Caspase 3, and cleaved-Caspase 3 levels within tumor tissues, were examined." (PMID 34395239, 2021).
tumor (continued). "We further assessed the protein expression of proliferation biomarkers KI67 and PCNA in tumor tissues." (PMID 34221996, 2021). "In ex vivo experiments, immunohistochemistry (IHC) and immunofluorescence (IF) showed that the expression of HSP70 increased and that of PCNA decreased, and many apoptotic tumor cells were observed by TUNEL staining in the IR780-NBs-DTX group." (PMID 33737559, 2021). "Ki67 and PCNA staining of the subcutaneous tumor further confirmed that the ectopic expression of LINC01050 promoted GC cell proliferation in vivo." (PMID 34749766, 2021). "IHC analysis revealed a decline of Ki-67 and PCNA expression in xenograft tumor tissues derived from sh-BBOX1-AS1-transfected cells." (PMID 33931086, 2021). "Immunohistochemical analysis of the tumors revealed that tumors formed by the WT cells expressed higher levels of PCNA compared with those formed by the KO cells (p = 0.02), indicating that the WT tumor cells proliferated at a higher rate." (PMID 33600074, 2021). "In line with the EdU and CCK-8 assays results in vitro, IHC staining of the xenograft tumor tissue demonstrated that the PCNA expression was significantly decreased in the SCH772984 treated xenografts (SS4+DMSO vs. SS4+SCH)." (PMID 33816264, 2021). "To better understand the increased tumor burden in the aneuploid group, we measured the proliferation of tumor cells using two different markers, PCNA and Ki67." (PMID 34885137, 2021). "Immunohistochemical results further showed that cleaved caspase-3, LC3B-II, and p-JNK levels were significantly increased whereas that of proliferating cell nuclear antigen (PCNA) was decreased in the tumor tissues after peiminine treatment." (PMID 34867399, 2021). "The PCNA expression in tumor tissue is shown in the images, which represent the mean expression of the marker in the studied group." (PMID 33716589, 2021). "Meanwhile, immumohistochemical staining of the tumor tissues showed that miR-155-5p-deleted exosomes decreased the expression level of PCNA and Ki67 compared to the NC groups, indicative of lower capabilities of tumor growth." (PMID 34131104, 2021). "Compared to xenografts from the control group, LOXL2 knockdown robustly repressed tumor growth, which was further confirmed by IHC staining of the proliferation index PCNA." (PMID 34836938, 2021). "On the other hand, MCM proteins are very sensitive markers of proliferation because they are expressed in both replication-competent and actively proliferating cells, staining a higher number of cells in tumour specimens than PCNA or Ki-67." (PMID 34073937, 2021). "PCNA is the most commonly used indicator for detecting tumor cell proliferation activity in recent years." (PMID 34721621, 2021). "Most PCNA positive cells appeared at the edges of tumor tissues to rapidly develop tumor growth and regions between the adipose and tumor tissues." (PMID 34638514, 2021). "Our data show that Fr-BuVt can suppress mTOR, ERK, NFκB and PCNA expressions in Ehrlich carcinoma-bearing mice tumor." (PMID 33413302, 2021). "AKF-D52-treated tumor tissues showed reduced expression of proliferating cell nuclear antigen (PCNA), a marker protein for cell proliferation." (PMID 34831003, 2021). "(G and H) Immunohistochemical staining for proliferating cell nuclear antigen (PCNA) of tumor tissues." (PMID 34528509, 2021). "CircCHST15 located in the cytoplasm promoted tumor growth, down-regulated the expressions of miR-155-5p and miR-194-5p, and up-regulated the expressions of PD-L1, Ki-67, PCNA, CCL17, CCL22, IFN-γ, TNF-β, and IL-10." (PMID 33777742, 2021).
tumor (continued). "To investigate the effect of YM101-stimulated immunity on tumor cells, we conducted IHC staining for anti-Ki67, anti-PCNA, anti-cleaved-Caspase 3 using EMT-6 tumor samples." (PMID 33593403, 2021). "Amino acid PET imaging such as ammonia, methionine, FET, FLT, FDOPA deals with part of tumor biology related to histopathology with the Ki-67 index, proliferating cell nuclear antigen, and microvessel density." (PMID 34630267, 2021). "All the findings demonstrated that downregulation of FBXO43 inhibited the tumor growth of BC by limiting its interaction with PCNA." (PMID 34645483, 2021). "The tumor tissues with circNDUFB2 overexpression had lower expression of Ki67 and PCNA than the vector group." (PMID 33436560, 2021). "Staining tumour tissue for proliferating cell nuclear antigen (PCNA) showed that consumption of black tea extract reduced tumour proliferation in the mice by 11%." (PMID 33668434, 2021). "Immunohistochemical analysis of panobinostat-treated tumour tissue revealed a significant reduction in cell proliferation compared to vehicle control, as assessed by PCNA staining (vehicle, 93.7 ± 5.1 vs. panobinostat, 79.6 ± 4.5; p < 0.0001." (PMID 34680294, 2021). "As compared to the control group, expression of cyclin D1, Ki-67 protein, and proliferating cell nuclear antigen was decreased in tumor tissues in the group treated with metformin and DCA was decreased." (PMID 34576192, 2021). "One to two weeks after the end of TMZ exposure, the tumor growth (PCNA expression) of SurvNESmut-GFP xenografts was reduced." (PMID 34100981, 2021). "Analysis of tumor sections showed higher expression of PCNA in obese-vehicle as well as obese-tamoxifen group in comparison to tamoxifen-treated lean-mice." (PMID 34389732, 2021). "Some size differences were also found with larger tumors obtained upon injection of NME2 KO cells, which correlated with higher percentage of PCNA-positive cells in NME2-KO tumor xenografts as compared to NT or NME1-KO tumors." (PMID 34012098, 2021). "The combined administration of imatinib and CPT triggered a decrease on PCNA expression by 80.14% in tumour tissue." (PMID 34214017, 2021). "This was confirmed by the immunohistochemical results that co-administration of rapamycin and trametinib reduced the number of PCNA-positive tumor cells compared with the single-agents treatment." (PMID 34421360, 2021). "Consistent with our in vitro findings, AKF-D52-induced apoptosis was confirmed in tumor tissues of the A549 xenograft model mice based on IHC with PCNA and TUNEL assays." (PMID 34831003, 2021). "Compared to other groups, the high-dose treatment groups showed reduced fibrous tissue proliferation, inflammatory cell infiltration, and necrosis in tumor cells; these groups also showed reduced expression of PCNA and VEGF." (PMID 34257693, 2021). "Carboplatin (60 mg/kg) was delivered by a single tail-vein injection, and tumours were harvested at 3 days post treatment and analysed by IHC for cell size and PCNA-positive staining." (PMID 33983115, 2021). "The results suggested that the expression of Ki-67 and PCNA on tumour tissues dramatically decreased in the combination treatment group compared to the control group." (PMID 34214017, 2021). "In contrast with CHAF1B, CHAF1A protein expression inversely correlates with PCNA levels and is downregulated in aggressive tumours." (PMID 34073937, 2021). "Consistently, the western blot assay also showed that Ki-67 and PCNA protein expression was reduced in tumor tissues derived from sh-THAP9-AS1-transfected cells." (PMID 33854048, 2021). "Knockdown of H19 slowed tumor growth, promoted apoptosis, and upregulated miR-20b-5p expression, but lowered the expression of PCNA in vivo, thereby providing a novel target for diagnosing and treating EC." (PMID 34721621, 2021).